CYP19A1 (cytochrome P450 family 19 subfamily A member 1)
Diseases named in the same sentence as CYP19A1 in open-access papers (continued):
Sharing a sentence is not in itself a finding about the gene and the disease.
breast cancer (continued). "Finally, in hormone-dependent prostate and breast cancers, CYP17A1 and CYP19A1 are targeted by inhibitors for cancer treatments." (PMID 31258835, 2019). "In our in silico analysis, we recently showed that, apart from repressing MYC, ras, and HMGA2, let-7 may also target CYP19A1, ESR1, and ESR2, thereby potentially blocking estrogen signalling in er-positive breast cancers." (PMID 20179807, 2010). "However, other studies did not reveal prognostic significance of CYP19A1 mRNA and aromatase enzyme activity in women with postmenopausal breast cancer or ER positive." (PMID 34133482, 2021). "However, no study has evaluated CYP19A1 gene expression in the peripheral blood of women with relapsed breast cancer." (PMID 32460723, 2020). "Whereas StAR and key steroidogenic enzyme genes evaluated (CYP11A1, HSD3B, CYP17A1, CYP19A1, and HSD17B) were altered to varying levels in these hormone responsive cancers, amplification of the StAR gene was correlated with poor overall survival of patients afflicted with breast cancer." (PMID 31060224, 2019). "This study identified a new potential AI-treatment predictive marker in CYP1A2 rs762551 for early breast cancer events, and the results indicate that CYP1A2 rs762551 in combination with CYP19A1 rs4646 or AhR Arg554Lys may yield even better treatment prediction." (PMID 27029552, 2016). "Moreover, TAM and G1 induced CYP19A1 gene expression and increased E2 production, also via the GPER/EGFR/ERK pathway, providing novel insights into the estrogenic effects on the breast cancer microenvironment and the induction of TAM resistance in a CAF-dependent manner." (PMID 24481325, 2014). "However, according to a survey of the literature, the evaluation of CYP19A1 mRNA by quantitative RT-PCR in the total blood of women with breast cancer recurrence was not reported, but some studies solely involving normal, peritumoral and tumoral tissues are available." (PMID 32460723, 2020). "The hormonal-related genes studied (ESR1, CYP19A1, and PGR) were not expressed by MCF10-DCIS cancer cells that are HER2-enriched (ER−, PR−, HER2+/ERBB2+) intrinsic molecular subtypes of breast cancer." (PMID 39072314, 2024). "The group of women with recurrence of breast cancer and negative HER2 receptor expression showed reduced CYP19A1 mRNA levels compared to those with positive HER2 receptor expression (p < 0.0376)." (PMID 32460723, 2020). "Meanwhile, CYP19A1 is upregulated in the ER positive cell lines (MCF-7, BT-474) of all the 5 breast cancer cell lines, with the highest expression in BT-474, while almost no expression in ER negative breast cancer cell lines." (PMID 35657638, 2022).
endometriosis (39 papers, 2005 to 2025). The growth of functional endometrial tissue in anatomic sites outside the uterine body. "In vitro studies demonstrated that 8-Br-cAMP treatment of ESCs from the eutopic endometrium of endometriosis patients increases CYP19A1 expression while decreasing HSD3B1 (which encodes the pregnenolone to P4 converting enzyme)." (PMID 40072055, 2025). "Our results indicate that carriers of the TC/CC genotype in CYP19A1 appear to be more susceptible to developing endometriosis." (PMID 37107315, 2023). "Two studies indicated an association of rs2899470 and 1531 G > A of the CYP19A1 gene with endometriosis." (PMID 37107315, 2023). "The gene encoding ARO, CYP19A1, was detected in all endometriosis tissue at levels all greater than found in control; STS and HSD17B1 presented consistently higher mRNA expression levels in DIE." (PMID 35591944, 2022). "Literature data indicate that studies draw attention to the significant role of estrogen receptor genes, especially the ESR2 gene and the CYP19A1 gene for the susceptibility and occurrence of endometriosis." (PMID 34638893, 2021). "Recent studies have shown that the polymorphisms rs17179740 of the ESR2 gene and rs2899470 of the CYP19A1 gene are associated with the occurrence of endometriosis." (PMID 34638893, 2021). "The genes for progesterone and estrogen receptors, including ER, PR, HSD17B1, CYP17, and CYP19A1, have been found to have an association with endometriosis." (PMID 32370117, 2020). "The risk for the occurrence of endometriosis is evaluated in association with the polymorphisms of various genes, participating in the biosynthesis of estrogens, including CYP19A1 and ESR2." (PMID 33153202, 2020). "Literature data indicate the particular role of estrogen receptor genes, especially of the ESR2 gene and of the CYP19A1 gene for the susceptibility to and the incidence of endometriosis." (PMID 33153202, 2020). "According to most recent studies, ESR2 and CYP19A1 genes may account for the potential risk factors of infertility associated with endometriosis." (PMID 33153202, 2020). "However, not all reports confirm the correlation of SNP polymorphisms of the CYP19A1 gene with endometriosis." (PMID 33153202, 2020). "Based on these results, they hypothesized that the reduced CYP19A1 gene expression in cumulus cells might partly account for the impaired oocyte quality associated with endometriosis." (PMID 29743986, 2018). "Endometriosis is dependent on estrogen, and genetic variations in estrogen receptors (ER-α and ER-β) as well as enzymes involved in estrogen synthesis, such as aromatase (encoded by the CYP19A1 gene), may predispose individuals to increased susceptibility and severity." (PMID 40217609, 2025). "They investigated the effect of bazedoxifene and medroxyprogesterone acetate on the expression of PR, ER, and aromatase enzyme (CYP19A1) genes in the cell culture media obtained from the patient biopsy with endometriosis." (PMID 39355309, 2024). "Our results showed that CYP19A1 was detected in all endometriosis tissues and was in higher levels than in control." (PMID 35591944, 2022). "Local E2 levels are increased in endometriosis due to upregulation of the aromatase gene CYP19A1 and reduction of 17-hydroxysteroid dehydrogenase type 2 (17HSD2), which normally (induced by P4) converts E2 to the less potent estrone." (PMID 34405378, 2022). "The latest research indicates a correlation of rs2899470 and 1531G > A of the CYP19A1 gene with endometriosis." (PMID 33153202, 2020). "The basis of the observed changes is not yet identified for the time being, therefore, the goals of the study included the demonstration of correlations between the level of the CYP19A1 gene expression and the incidence of endometriosis." (PMID 33153202, 2020). "The results of experimental study, concerning the analysis of ESR1, ESR2, PGR, and CYP19A1 genes, unveil the existence of certain correlations of their expression with endometriosis." (PMID 33153202, 2020).
endometriosis (continued). "Other xenobiotic metabolic enzymes like aromatase P450 family members CYP1A1 and CYP19A1 also have a fundamental role in the pathogenesis of endometriosis, and have been widely studied and applied to endometriosis treatment." (PMID 31881062, 2019). "In conclusion, microRNA Let‐7b treatment of endometriosis resulted in decreased oestrogen signalling (ER and Cyp19A1), decreased KRAS and decreased inflammatory signalling (IL‐6)." (PMID 30063121, 2018). "We examined the association of estrogen receptor ESR2 and estrogen biosynthesis enzyme, aromatase, CYP19A1 with endometriosis and breast cancer." (PMID 26512648, 2015). "They reported significantly increased P450 aromatase (CYP19A1) expression in endometriosis patients: 32.4% of the endometriosis patients presented moderate expression, and 67.6% presented strong expression, with no cases of negative or weak expression observed." (PMID 40909174, 2025). "Due to the small amount of research on the analysis of CYP19A1 and ESR2 gene expression and polymorphisms in patients with endometriosis, the research makes a significant contribution to expanding the knowledge about the impact of genetic factors on the development of endometriosis." (PMID 34638893, 2021). "Learning and understanding the relationships between ESR2 and CYP19A1 gene expression and endometriosis may help design and develop new therapeutic concepts and strategies in the context of the disease." (PMID 33153202, 2020). "Let-7b treatment of endometriosis could decrease inflammatory signaling (IL-6), decreased estrogen signaling (ER and Cyp19A1), and also decrease KRAS." (PMID 32850438, 2020). "A reduced CYP19A1 expression in endometriosis may result from epigenetic modifications in the regulatory regions of the gene as, for example, DNA methylation or from the modification of histones." (PMID 33153202, 2020). "A significant increase of ESR2 and CYP19A1 gene expression was observed in the studied groups of women with endometriosis, which may indicate a certain role of this factor in the pathogenesis of endometriosis." (PMID 33153202, 2020). "Nevertheless, SF-1, expressed in eutopic and ectopic endometria from women with endometriosis, aberrantly activates CYP19A1 and the expression of P450Arom in stroma or gland in these tissues as has been extensively described favoring this estrogenic microenvironment in this disease." (PMID 26453052, 2015). "Although two types of USF, USF1 and USF2, have been reported, it is USF2 that shows the highest binding activity on SF-1 promoter and its knockdown results in down-regulation of SF-1 and also of its target gene CYP19A1 in ectopic endometrium from endometriosis women." (PMID 26453052, 2015). "Gene expression ratio among CYP19A1, STS, and HSD17B1 in biopsies from endometriotic lesions and from eutopic endometrium of non-endometriosis patients (control)." (PMID 35591944, 2022). "Five estrogen-responsive genes, CYP19A1, EGFR, ESR2, FOS, and IGF1, were found to be modified in human endometriosis, uterine tumor and breast tumor tissues." (PMID 36401252, 2022). "GNRH1, PGR, TNF, CYP19A1, and IL6 were mentioned with the highest frequencies in endometriosis-related articles." (PMID 34917684, 2021). "As observed when LXA4 was administered on D−1, IL-1β, COX-2, VEGF, MRP4, TGF-β1, TGF-β2, CYP19a1, ERα, GREB1 and c-Myc expression were significantly attenuated whereas MMP-9 and TGF-β3 were upregulated in endometriotic lesions in established endometriosis." (PMID 24587003, 2014). "The authors demonstrated a lower CYP19A1 expression in CCs of infertile patients with endometriosis compared with infertile women without endometriosis." (PMID 29743986, 2018).
endometriosis (continued). "In consideration of the rather small number of studies on the expression and CYP19A1 and ESR2 gene in patients with endometriosis, the assumed impact of experimental studies may bring a real added value, extending our knowledge of the effects of genetic factors on the development of endometriosis." (PMID 33153202, 2020).
polycystic ovary syndrome (38 papers, 2009 to 2025). A disorder that manifests as multiple cysts on the ovaries. "We focused instead on answering clearly-predefined questions regarding the potential contribution of the CYP19A1 variant to polycystic ovarian disease (through genotype-phenotype correlations)." (PMID 24954083, 2014). "As a result, we were not able to reach a definitive conclusion on the pathogenicity of rare variants in CYP19A1 for polycystic ovarian syndrome." (PMID 24954083, 2014). "Additionally, CYP19A1-deficient girls develop ovarian cysts similar to those found in polycystic ovarian syndrome." (PMID 39056753, 2024). "Another polymorphism study was performed in Iranian women and 140 people in this case–control study to ascertain a link between rs2414096 CYP19A1 and polycystic ovary syndrome; outcomes revealed that the rs2414096 variant was significantly involved in the probability of individuals developing PCOS." (PMID 35205347, 2022). "Hyperandrogenemia impedes granulosa cell aromatase (CYP19A1) activity, thereby interrupting oestradiol production and resulting in follicular arrest during the pre-antral and early antral phases." (PMID 41010046, 2025). "As a result, the stimulatory effect of androgen on FSH and subsequently, on the expression of Cyp19a1 was reduced in the polycystic ovary of rats." (PMID 37147728, 2023). "CYP19A1 is considered to be an important marker in the etiology of polycystic ovary syndrome." (PMID 35250857, 2022). "In polycystic ovarian syndrome (PCOS), where epigenomic instability affects Fshr, Cyp19a1, Esr1, and Igf1, PFASs intensify transcriptional repression through DNMT3A-mediated CpG hypermethylation and global hypoacetylation of H3K9 and H4K16." (PMID 40724853, 2025). "Other studies demonstrated decreased expression of FSHR and CYP11A1 and increased expression of CYP19A1, STAR, HSD3B2 and INHBA in polycystic ovary granulosa cells compared to controls." (PMID 36768772, 2023). "MT promotes the expression levels of CYP19A1 and HO-1 in human ovarian GCS, reduces the level of IL-18, and promotes the oocyte maturation in PCOS patients with hyperandrogenemia." (PMID 34228638, 2021). "According to the study, women with polycystic ovary syndrome had lower average mRNA CYP19A1 expression for aromatase in granulosa cells than women without polycystic ovary syndrome." (PMID 39618718, 2024). "Patients with polycystic ovary syndrome may have follicle development impairment due to elevated levels of estrogen and pregnenolone in follicular fluid; the mechanism is in part mediated by changes in the expression of HSD17B1, CYP19A1, and CYP11A1 in FF exosomes." (PMID 36210808, 2022).
Obesity (27 papers, 2012 to 2026). Accumulation of substantial excess body fat. "CYP19A1 was also found to be associated with cardiovascular risk factors such as insulin resistance and hypertension in a sex- and obesity- specific manner." (PMID 32814585, 2020). "Nonetheless to respond the all the causes of dyslipidemia and obesity we are also investigating other SNPs that have been previously asssociated to this illness, like SNPs on genes such as CYP19A1, ESR2 and PGR." (PMID 28199328, 2017). "Obesity is also associated with CYP19A1 as adipose tissue has the highest level of CYP19A1." (PMID 40141105, 2025). "Large prospective cohorts should examine interactions between obesity-related genetic polymorphisms (e.g., CYP19A1, PTEN, PIK3CA), adipokine expression profiles, and metabolomic signatures to delineate high-risk phenotypes requiring intensified preventive surveillance." (PMID 41301707, 2025). "Such a ‘two-hit’ mechanism of derepression (hypomethylation) and activation (e.g., obesity-related cytokines) may also explain why CYP19A1 hypomethylation was associated with early B2 in overweight, but not normal weight girls in the present study." (PMID 24649863, 2014). "Recently, a case-control study on associations between CYP19A1 polymorphisms and obesity in Turkish population illustrated that the reduced aromatase activity is a risk factor for obesity, and CYP19A1 is associated with hyperandrogenism which may play a role in abdominal obesity pathogenesis." (PMID 32814585, 2020). "The concept of a hypogonadal–obesity–adipokine cycle is a proposed mechanism behind this association: Obesity has been suggested to lead to enhanced aromatisation of androgens to oestrogens by aromatase (CYP19A1) in adipose tissue, thereby reducing the level of active androgens." (PMID 28566439, 2017). "In parallel with the decrease in testosterone levels, the expression of P450Scc, StAR, and 17βHSD genes significantly decreased and CYP19A1 expression increased in the obesity group compared to the control group (p < 0.05)." (PMID 36644444, 2023). "The generation of Esr1−/− and Cyp19a1−/− mice revealed that ESR1 and aromatase deficiency leads to the development of obesity and insulin resistance." (PMID 33430527, 2021). "In summary, our findings of an association between the CYP19A1 gene variants and circulating HGF levels offer a novel mechanism underlying the link between obesity and endocrine-related diseases." (PMID 22848710, 2012). "Similarly, PTGS2(prostaglandin-endoperoxide synthase 2) and CYP19A1(cytochrome P450 family 19 subfamily A member 1) are also predicted to be pivotal target for reducing or reversing hyperlipidemia and obesity." (PMID 38246999, 2024). "Because obesity is associated with increased aromatase activity, it is not surprising that women with high WC had increased CYP19A1 expression in breast adipose tissue." (PMID 34426770, 2021). "Indeed, people with obesity have been reported to have increased CYP19A1 expression in WAT." (PMID 41180177, 2025). "Furthermore, CYP19A1 transcript levels and activity are amplified in obesity." (PMID 35049520, 2022). "The common targets of obesity, T2DM, and AS are estrogen receptor 2 (ESR2), androgen receptor (AR), CYP19A1, NR3C1, SRC, and arachidonate 5-lipoxygenase (ALOX5)." (PMID 39575382, 2024). "Top findings within the block involved well-known obesity genes such as the FTO, the CYP19A1 and the USF-1." (PMID 31527397, 2019). "Increased adipose tissue in obesity leads to higher levels of circulating estrogen synthesized and metabolized by the cytochrome P450 (CYP) superfamily of enzymes, specifically aromatase CYP19A1." (PMID 39767708, 2024). "The core targets between estrogen and obesity are proto-oncogene, non-receptor tyrosine kinase (SRC), estrogen receptor 1 (ESR1), prostaglandin-endoperoxide synthase 2 (PTGS2), nuclear receptor subfamily 3 group C member 1 (NR3C1) and cytochrome P450 family 19 subfamily A member 1 (CYP19A1)." (PMID 39575382, 2024).